ZNF385D (zinc finger protein 385D)
Synonyms: ZNF659; FLJ22419
Tractability: PROTAC: ubiquitination databases record sites on it.
Gene: Protein-coding gene on chromosome 3 (21,412,218 to 22,373,321, reverse strand). Ensembl gene ENSG00000151789.
Subcellular location: Nucleus
Gene Ontology:
Molecular function: sequence-specific double-stranded DNA binding; nucleic acid binding; zinc ion binding
Cellular component: nucleus
Genetic constraint (gnomAD): Loss-of-function variants: 11 observed, 29.78 expected, observed/expected ratio (o/e) 0.37, 90% interval 0.23 to 0.61. The upper end of that interval is the gene's LOEUF score, 0.61, which puts it in group 2 of 6, group 1 being the genes least tolerant of losing a copy. Missense variants: 430 observed, 463.46 expected, observed/expected ratio (o/e) 0.93, 90% interval 0.86 to 1. Synonymous variants: 191 observed, 175.82 expected, observed/expected ratio (o/e) 1.09, 90% interval 0.96 to 1.23.
Homologues: Orthologues: chimpanzee ZNF385D (100% identical), macaque ZNF385D (100% identical), rabbit ZNF385D (99% identical), pig ZNF385D (99% identical), guinea pig ZNF385D (98% identical), dog ZNF385D (97% identical), tropical clawed frog znf385d (78% identical), zebrafish znf385d (37% identical), Drosophila melanogaster dbf (21% identical), Drosophila melanogaster CG1231 (17% identical). Paralogues in human: ZNF385B (59% identical), ZNF385A (46% identical), ZNF385C (43% identical), ZMAT3 (15% identical), ZMAT1 (12% identical), ZNF346 (11% identical), ZMAT4 (11% identical), ZMAT2 (10% identical), KRCC1 (5% identical).
Diseases named in the same sentence as ZNF385D in open-access papers:
ZNF385D is named in the same sentence as 12 diseases in open-access papers, as found by Europe PMC text mining. Sharing a sentence is not in itself a finding about the gene and the disease. The quoted sentences say what the papers report.
COVID-19 (2 papers, 2024). A disease caused by infection with severe acute respiratory syndrome coronavirus 2. "MYBL2 was listed in the context of neutrophil degranulation during COVID-19, while ZNF385D was identified in an epigenome-wide association study (EPICOVID)." (PMID 38674024, 2024). "For example, ZNF385D and CPSF2, which are both repressed by the S1 subunit, are associated with COVID-19-related inflammation and stroke." (PMID 38674024, 2024). "A recent epigenetic study on post-COVID-19 patients found a significantly differentially genomic region located in the vicinity of the ZNF385D gene by comparing severe versus mild COVID-19 patient groups (p = 4.82 × 10−14)." (PMID 38397203, 2024). "On the other hand, PNMA8A/PNMAL1 was also listed among stroke candidate genes, and ZNF385D and CPSF2, which are repressed by the S1 subunit, were also associated with inflammation and stroke in relevance to COVID-19." (PMID 38674024, 2024). "ZNF385D and MYBL2 were both listed as hub genes in a study examining the influence of COVID-19 on ischemic stroke." (PMID 38674024, 2024).
atherosclerosis (1 paper, 2024). A disease characterized by the build-up of fatty material and calcium deposition in the arterial wall resulting in partial or complete occlusion of the arterial lumen. "The extremely strong CIMT association from our inferred gene expression networks under the regulation of genetically polymorphic ZNF385D and HAND2 is in support of genetically controlled functional pathways independent of lifestyle and behavior factors in the development of atherosclerosis." (PMID 38397203, 2024).
dyslexia (1 paper, 2018). A learning disorder characterized by an impairment in processing written words. "However, it is worth noting that GWAS for dyslexia have been under‐powered so far and variants with the strongest association to dyslexia (e.g., in genes RBFOX2, ABCC13, ZNF385D, COL4A2 and FGF18) failed to survive genome‐wide statistical scrutiny." (PMID 30218584, 2018).
intracerebral haemorrhage (1 paper, 2019). "We identified two variants near SPTLC3 and ZNF385D that modulate the plasma levels of CER (d18:1/24:1) and CER (d18:1/24:0), respectively, and risk for intracerebral haemorrhage." (PMID 31551469, 2019). "We found that the CER (d18:1/24:1) decreasing variant SPTLC3 rs364585-G was associated with decreased risk of intracerebral haemorrhage, while CER (d18:1/24:0) increasing variant ZNF385D rs13070110-C was nominally associated with increased risk of intracerebral haemorrhage." (PMID 31551469, 2019).
ischemic stroke (1 paper, 2024). A stroke disorder caused by obstruction of blood flow to the brain, due to thrombotic (local blood clot formation) or embolic (due to a blood clot or other material traveling from another site) event. "Both ZNF385D and MYBL2 are amongst the hub genes identified to explain the impact of COVID-19 on ischemic stroke." (PMID 38674024, 2024).
learning disabilities (1 paper, 2025). "Additionally, SNPs in ZNF385D are connected to language-based learning disabilities and impairments." (PMID 41214597, 2025).
Venous thrombosis (1 paper, 2025). Formation of a blood clot (thrombus) inside a vein, causing the obstruction of blood flow. "Variants near ZNF385D are linked to increased blood levels and a higher risk of arterial and venous thrombosis." (PMID 41214597, 2025).
ZNF385D also shares sentences with these, for which no sentence is quoted: attention deficit-hyperactivity disorder (1 paper); bipolar disorder (1); carotid atherosclerosis (1); schizophrenia (1); Stroke (1).